RNY4P6 (RNY4 pseudogene 6)
Gene: Miscellaneous RNA gene on chromosome 11 (117,015,897 to 117,015,992, forward strand). Ensembl gene ENSG00000200537.
Homologues: Orthologues: chimpanzee Y_RNA (97% identical), guinea pig Y_RNA (94% identical), rabbit Y_RNA (94% identical), rabbit Y_RNA (93% identical), rabbit Y_RNA (92% identical), rabbit Y_RNA (91% identical). Paralogues in human: RNY4 (96% identical), RNY4P13 (91% identical), RNY4P7 (91% identical), Y_RNA (91% identical), RNY4P10 (90% identical), RNY4P17 (90% identical), RNY4P19 (90% identical), RNY4P25 (90% identical), RNY4P3 (90% identical), Y_RNA (90% identical), RNY4P14 (89% identical), RNY4P23 (89% identical), and 91 more.